IL13RA2 (interleukin 13 receptor subunit alpha 2)
Diseases named in the same sentence as IL13RA2 in open-access papers (continued):
Sharing a sentence is not in itself a finding about the gene and the disease.
tumor (continued). "The IL13 receptor α2 (IL13RA2) has been shown to suppress sunitinib-mediated apoptosis without enhancing tumor angiogenesis in the treatment of KIRC." (PMID 40612864, 2025). "To test the relevance of IL13RA2 in the metastatic setting, we performed intracardiac injection of MDA231BrM2-CTL or MDA231BrM2-ΔIL13RA2 cells in immunocompromised nude mice and tracked tumor development over four weeks." (PMID 40663259, 2025). "By bridging IL-13Rα2+ tumor cells and CD3ε on T cells, the BiTE induces T-cell activation (CD69/CD25 upregulation), GZMB release, and production of inflammatory cytokines (IFN-γ, TNF-α), culminating in tumor-specific lysis." (PMID 41209565, 2025). "Treatment with IL-13Rα2/TGF-β CAR-T cells in human and mouse GBM models has demonstrated increased T cell infiltration, reduced levels of suppressive myeloid cells in the tumor-bearing brain, and improved survival rates in patient-derived GBM xenografts and syngeneic mouse models." (PMID 40303292, 2025). "For example, intracranial or intraventricular delivery strategies have been used in clinical studies targeting IL-13 receptor alpha 2 (IL-13Rα2) and HER2 in GBM patients, which has led to increased CAR T cell accumulation at the tumor site and, in certain cases, tumor regression." (PMID 40585996, 2025). "In sharp contrast, the CAR‐T cells made basal and minimal amount to IFN‐γ when cultured with IL‐13Rα2 negative or IL‐13Rα2 KD tumour cell line." (PMID 38685487, 2024). "The IL-13Rα2 DNA vaccine, in combination with IL13-PE (a chimeric pseudomonas exotoxin), synergized to reduce murine breast tumor growth by multiple mechanisms, including direct tumor killing and increased T-cell tumor infiltration." (PMID 38612592, 2024). "The study demonstrated that these scFv-IL-13Rα2-CAR-T cells exhibited significant antitumor activity in vitro and in vivo, effectively killing IL-13Rα2-positive tumor cells while showing low toxicity in non-tumor-bearing mice." (PMID 39506843, 2024). "Additionally, we performed Western blot experiments using available BSG cells, which similarly indicated elevated expression levels of IL13Ra2 and CD133 in H3K27M mutant-type tumor cells." (PMID 38201655, 2024). "Furthermore, IL-13Rα2, a TSA, is highly expressed in GBM tumor cells but is seldom found in normal brain cells, making it a compelling target for CAR-T cell therapy in GBM." (PMID 39697210, 2024). "This second CAR is responsible for killing cancer cells by recognizing antigens such as EphA2 or IL13Rα2, which are uniformly expressed in cancer cells but not tumor-specific." (PMID 39506843, 2024). "When the surviving mice were rechallenged with a parent tumor line (IL13Rα2 negative), the STING KO mice demonstrated a modestly reduced antitumor response and survival benefit." (PMID 38994929, 2024). "All these findings indicate that IL13Ra2 is a good target for CAR-T-cell therapy and other therapeutics since it leads to the specific killing of cancer cells that are the most resistant to current therapeutics and, thus, the origin of tumor recurrence." (PMID 38201655, 2024). "In contrast, both labeled and non-labeled CAR-T cells secreted basal and minimal amounts of IFN-γ when cultured with IL-13Rα2 negative tumor cell line." (PMID 37286997, 2023). "The precise etiology of relapse has yet to be fully understood; nevertheless, there have been documented cases of tumor recurrence accompanied by the diminished or absent expression of IL13Rα2, as reported in the following studies." (PMID 38002496, 2023). "Using the tumor line A549, which endogenously expresses IL13Rα1, but not IL13Rα2, we found that the IL13-28ζ CAR T cells exhibited the most off-target–mediated degranulation, activation marker expression, in vitro cytotoxicity, and proliferation." (PMID 36968221, 2023). "Similarly, IL13Rα2 up regulates transforming growth factor β (TGF-β) in immune cells thus promotes progression and tumor immune escape." (PMID 35612318, 2022).
tumor (continued). "Therapeutic targets tested in initial phase I/II trials included interleukin-13 receptor subunit alpha-2 (IL-13Rα2), EGFRvIII, and human epidermal growth factor receptor 2 (HER2), chosen because of the selective expression in tumor cells compared to healthy brain cells." (PMID 35267432, 2022). "One individual with multifocal recurrent GBM achieved complete tumor remission, even though the tumor did not homogenously express IL13Ra2 target antigen." (PMID 35606815, 2022). "In our study, the trend of the expression level of IL13RA2 was also up-regulated in tumor samples compared with normal samples, though it was not significant (P = 0.0918)." (PMID 35748788, 2022). "CLTX was demonstrated to bind the majority of tumor cells in more than 90% of tested tumor samples, with little to no reactivity with healthy brain and independently from the expression of other targets as IL-13Rα2, EGFRvIII, and HER2." (PMID 35267432, 2022). "Interestingly, IL-13Rα2-depleted-U87 glioma cells exhibited a marked decrease in the expression of p-PI3K and its downstream target gene p-Akt and p-mTOR, thus restricting tumor growth." (PMID 34439380, 2021). "IL13Rα2+ U87 cells were implanted into nude mouse brains, and YYB-103 CAR or UnTd T cells were injected i.c.v. into mice 15 days after xenograft of U87 cells following confirmation of tumor growth by bioluminescence." (PMID 34819930, 2021). "Several IL13Rα2-targeting therapies, including chimeric antigen receptor (CAR) T cells targeting IL13Rα2, IL13Rα2-targeted immunotoxins, IL13-expressing virus, anti-IL13Rα2 antibody therapy, and IL13Rα2-targeted tumor vaccine, have been tested in clinical trials and found to be safe." (PMID 34819930, 2021). "Activation of IL-13Rα2 by CHI3L1 triggers the activation of the mitogen-activated protein kinase signaling pathway, upregulating matrix metalloproteinase genes expression and promoting tumor metasta." (PMID 34722557, 2021). "Survival time in the mice with IL-13Rα2-positive tumor was significantly shorter than the mice with IL-13Rα2-negative tumors." (PMID 34201539, 2021). "On the other hand, IL-13 when bound to IL-13Rα2 in tumor cells does not recruit another chain but mediates signaling through a different pathway." (PMID 32443847, 2020). "In addition, we studied the involvement of IL13Rα2 and PTP1B in the tumor growth using xenograft tissues." (PMID 32098194, 2020). "Our results indicated that the expression of KLKB1 (P < 0.01), IL13RA2 (P < 0.01), ABCC8 (P < 0.01), and PART1 (P < 0.0001) was consistent with our bioinformatics analysis, which was significantly up-regulated in PanNETs compared with the non-tumor tissues." (PMID 31607839, 2019). "Therefore, to explore a more universal ACT for GBM patients, the Meenakshi group designed and validated trivalent CAR-T cells that simultaneously targeted HER2, IL13Rα2, and EphA2, which achieved nearly 100% clearance of GBM tumor cells." (PMID 31783889, 2019). "Although IL13Rα2 expression in the SK-MEL-28 cells slightly upregulated the expression of vascular endothelial growth factor (VEGF), a well-known tumour angiogenic factor, the upregulation can be considered minimal (1.5-fold), compared to that of amphiregulin (3.2-fold)." (PMID 30718742, 2019). "Our findings revealed that IL13Rα2 accelerated tumour growth in vivo not by promoting cell proliferation but rather by affecting in vivo tumour angiogenesis." (PMID 30718742, 2019). "Our immunohistochemical analysis by using anti-IL13Rα2 antibody (KH7B9), detected IL13Rα2 in the xenograft tumour cells derived from A375, but not in IL13Rα2-negative cells (A375-IL13RA2 KO and A2058 cells), thus confirming the specificity of the KH7B9." (PMID 30718742, 2019). "It is thus possible that subjects with IL-13Rα2 negative expression will have delayed tumor recurrence compared to subjects with IL-13Rα2 high expressing tumors and needs to be confirmed in larger sample database." (PMID 29168083, 2018).
tumor (continued). "They looked for IL13Ra2 presence in several carcinoma tissues and tested liposomal IL13-conjugated doxorubicin against glioblastoma tumors and in malignant peripheral nerve sheath tumors, demonstrating a decrease of tumor burden both in vitro and in vivo." (PMID 30404148, 2018). "Activation of IL-13Rα2 by CHI3L1 triggered the activation of the mitogen-activated protein kinase signaling pathway, leading to the upregulated expression of matrix metalloproteinase genes, which promoted tumor metastasis." (PMID 28143526, 2017). "Co-immunoprecipitation confirmed that IL-13Rα2 could interact with wtEGFR in Gli36.wtEGFR and tet-induced wtEGFR expressing U251-E6 cells, and in primary wtEGFR-positive GBM patient tumor." (PMID 29203859, 2017). "Furthermore, we demonstrated the use of PET/CT to evaluate tumor targeting after CED, which can be used to both ensure that the CED catheter is properly placed and to map successful targeting by putative IL13RA2 targeted therapies." (PMID 28562337, 2017). "In CRC clinical samples, we also find IL-13Rα1 expression level but not IL-13Rα2 is higher in CRC tissues when compared with adjacent non-tumor tissues at the mRNA levels." (PMID 27533463, 2016). "Histopathological analyses revealed that IL13RA2 repressed sunitinib-induced apoptosis without increasing tumor vasculature in vivo." (PMID 26114873, 2015). "However, we observed a high infection of IL13Rα2-expressing IL13Rα2+ U251MG xenograft; and once again there was no detectable GFP signal in the brain tissue adjacent to the tumor." (PMID 26656559, 2015). "No infection was detected in the mostly IL13Rα2-negative IL13Rα2.KDU251MG xenograft tissue or in the brain tissue surrounding the tumor as judged by the lack of GFP transgene expression." (PMID 26656559, 2015). "Sunitinib failed to suppress tumor growth of 786-O xenograft tumors when IL13RA2 was overexpressed, and sunitinib inhibited tumor growth of Caki-1 xenograft tumors knocked down for IL13RA2 in vivo." (PMID 26114873, 2015). "This may be due to a direct cytotoxic effect of IL-13-PE on MDSCs, since some of these myeloid cells are known to express IL-13Rα2 in order to induce TGF-β1 secretion and promote tumor immune evasion." (PMID 23421960, 2013). "IL13Rα2 is proposed to down-modulate IL13Rα1/IL4Rα receptor signaling by competing for IL13 binding, and to mediate TGF-β production in monocytes and tumor-infiltrating macrophages." (PMID 24204956, 2013). "Of note, endogenous tumor-produced TNF can have a remarkable protumorigenic activity, for instance by inducing expression of interleukin 13 receptor alpha 2 (IL13Rα2) on tumor resident monocytic cells and the subsequent production of the immunosuppressive cytokine TGF-beta." (PMID 23840967, 2013). "IL2-PE, a immunotoxin known to exert its cytotoxicity through binding to IL-2 receptor γ chain was not cytotoxic to IL-13Rα2 positive tumor cells confirming that IL-13-PE-mediated cytotoxicity is IL-13Rα2 specific." (PMID 23421960, 2013). "The MDSCs, however, may be particularly sensitive to IL-13-PE treatment since IL-13Rα2 has been shown to express on some populations of these myeloid cells in order to induce TGF-β1 secretion and promote tumor immune evasion." (PMID 23421960, 2013). "In contrast, when IL-13Rα2 was knocked-down prior to TSA therapy, the anti-tumor effect of combination of TSA and IL-13-PE was completely eliminated compared to mock vector transfected tumors, which showed dramatic tumor response." (PMID 21477288, 2011). "Using a well-characterized tumor toxicity assay, we analyzed the ability of various serum samples from mice systemically sensitized to IL13-PE to block the cytotoxicity of IL13-PE against IL-13Rα2-expressing tumor cells." (PMID 20090941, 2010). "Interestingly, mice vaccinated with therapeutic IL-13Rα2 cDNA vaccine and boosted with ECDα2 protein showed lower percentage of Tregs in the spleen and tumor compared to the PBS control in the MCA304 tumor model." (PMID 21067607, 2010).
tumor (continued). "In the present study, we demonstrate that engineered T cells expressing scFv‐huIL‐13Rα2 CAR proliferate, bind target antigen, and exhibit the cytotoxic activity to IL‐13Rα2 positive tumour cells, but not to IL‐13Rα2 negative tumour cells or IL‐13Rα2 gene silenced tumour cells." (PMID 38685487, 2024). "This analysis revealed that seven cell populations exhibited a significant correlation with poorer patient outcomes, including tumor cell cluster 3 (highly expressing S100A2), cluster 8 (TK1), cluster 10 (PTTG1), cluster 12 (IGFBP5), cluster 13 (ISG15), cluster 16 (UPP1), cluster 17 (IL13RA2)." (PMID 38331898, 2024). "General toxicity in non‐tumour bearing mice due to the CAR‐T cell administration was evaluated in non‐tumour bearing NOG mice because mice are not expected to express high levels of IL‐13Rα2 in any organ." (PMID 38685487, 2024). "However, in GBM, IL-13Rα2 competitively binds to IL-13, thereby inhibiting the STAT6 signaling pathway, promoting tumor cell invasion, metastasis, and proliferation, and inhibiting tumor cell apoptosis." (PMID 39506843, 2024). "Importantly, radiolabeling has minimal impact on biological product attributes including potency of CAR-T cells towards IL-13Rα2 positive tumor cells but not IL-13Rα2 negative cells as measured by cytolytic activity and release of IFN-γ." (PMID 37286997, 2023). "In gliomas, IL-13Rα2 expression is only detected in tumours and not normal brain tissue." (PMID 37455828, 2023). "Immunohistochemistry and western blotting analyses showed reduced protein expression of CHI3L1, PCNA, cyclin D1, Cdk 6, and MMP‐9, but the expression of cleaved caspase‐3 was increased; however, IL‐13Rα1 and IL‐13Rα2 levels were not changed in K284‐treated lung metastasis tumor tissues." (PMID 34758182, 2022). "However, among the 35 ACC patients with a new tumor event, the level of IL-13Rα2 expression did not have a significant effect on the survival rate." (PMID 33591997, 2021). "When the usefulness of PET/CT targeting IL-13Rα2 is established, it may be more useful for specific diagnoses of cancer compared to FDG-PET, as the latter reflects the cancer metabolism attribute of the tumor." (PMID 34201539, 2021). "The development of trivalent CAR-Ts specific to IL13Rα2, the human epidermal growth factor receptor (HER-2) and EGFRvIII, was made possible by analysing interpatient variability of multiple GBM samples, showing tumor cell-specific cytotoxicity and tumor remission in vitro and in vivo models." (PMID 34557553, 2021). "Additionally, many tumor antigens are restricted to specific HLA types (class I restricted cytotoxic T cell or class II restricted helper T cell epitopes), for example HER-2, IL13Ra2, MAGE-1, and survivin." (PMID 30790064, 2019). "The results showed that the expression of KLKB1 (P < 0.01), IL13RA2 (P < 0.01), ABCC8 (P < 0.01), and PART1 (P < 0.0001) was significantly up-regulated, while PCSK2 (P < 0.01) was significantly down-regulated in PanNET tissues compared to the non-tumor tissues." (PMID 31607839, 2019). "Furthermore, when subjects with IL-13Rα2 low (n = 113) and IL-13Rα2 negative (n = 122) tumor groups were combined together (n = 235), the median survival was significantly higher compared to subjects with high IL-13Rα2 expressing tumors (p < 0.003)." (PMID 29168083, 2018). "In our studies, we observed that CHI3L1, but not IL13, mediated IL‐13Rα2 activation which promoted tumor invasiveness, suggesting that these two ligands might promote differential signaling through IL‐13Rα2." (PMID 30094958, 2018). "ROI analysis of micro PET/CT imaging data showed that [64Cu]Pep-1L accumulation was ~3-fold greater in doxycycline-induced B16F10-Tet-hIL13RA2 tumor bearing mice compared to non-induced ones demonstrating specificity of [64Cu]Pep-1L to IL13RA2 expressing tumors." (PMID 28881623, 2017).
tumor (continued). "In addition, high IL-13Rα2 expression was shown to be an independent poor prognostic factor independent of depth of tumor invasion, lymph node metastasis status, and distant metastasis status for OS." (PMID 27351230, 2016). "Furthermore, we compared the IL-13Rα2 expression in CD11b+ cells recruited into OSC-19 tumours at non-IR and pre-IR sites by FACS analysis." (PMID 27271009, 2016). "Therefore, tumor tissue of KUCaP9 could not obtained for evaluating the expression levels of IL13Rα2 mRNA and protein." (PMID 36806727, 2023). "Notably, for both IL-13Rα2.IL15-CAR and MUC16ecto.IL-12-CAR T cells, IL-15 or IL-12 production was low at baseline and increased multiple fold in an antigen specific manner, indicating that elevated cytokine levels should be limited to the local tumor environment." (PMID 30828333, 2019). "The six tumor-associated antigens include: absent in melanoma 2 (AIM-2), melanoma-associated antigen 1 (MAGE-1), tyrosinase-related protein 2 (TRP-2), glycoprotein 100 (gp100), epidermal growth factor receptor 2 (HER-2), and interleukin-13 receptor subunit alpha-2 (IL-13Ra2)." (PMID 30150597, 2018). "Thus we conclude that while IL13Rα2 expression is not restricted to mesenchymal subclass tumors, its expression closely correlates with mesenchymal signature gene expression and thus presumably mesenchymal properties of a tumor." (PMID 24204956, 2013). "In a landmark case study, repetitive intracavitary and intraventricular IL13Rα2 CAR T cell administration in a GBM patient resulted in significant regression of intracranial and spinal lesions, with no off-tumor toxicities." (PMID 40868217, 2025). "Although we did not observe any correlations of IL13Ra2 expression with CD4/8 T-cell infiltration or HLA-1 expression, we noticed the HLA-1 expression was not suppressed in the majority of BSG tumor samples." (PMID 38201655, 2024). "We have previously reported that histone deacetylase (HDAC) inhibitors dramatically enhanced IL‐13Rα2 expression in receptor‐negative pancreatic cancer cells and in addition, HDAC inhibitors enhanced expression of IL‐13Rα2 in IL‐13Rα2 positive tumours." (PMID 38685487, 2024). "In univariate survival analysis, significant correlations were observed between poor OS and tumor grade, age, Ki67 and IDH but not IL-13Rα2 expression or nuclear and cytoplasmic FUS location." (PMID 37158824, 2023). "They found that CLTX-CAR T binds to 80% or more of tumor cells in 13/15 patient tumor samples, with the other two displaying 40% binding, regardless of HER2, IL13Ra2, or EGFR expression levels." (PMID 37754534, 2023). "This agent was designed to target the interleukin-13 receptor alpha-2 (IL13RA2), which has been demonstrated to be significantly overexpressed by ACC tumor cells compared to normal adrenal and nonmalignant tissues." (PMID 34071333, 2021). "In comparison to constitutively active anti-EGFRvIII/EphA2/IL13Rα2 CAR T cells, synNotch-CAR T cells showed greater anti-tumor efficacy without off-tumor toxicity." (PMID 34298615, 2021). "Pancreatic cancers in situ were not sensitive to IL-13-PE as they do not naturally express IL-13Rα2 and TSA or SAHA alone showed only modest to moderate anti-tumor effects." (PMID 21477288, 2011). "Tumor samples of IL-13Rα2 DNA and ECDα2 boost vaccine-treated mice collected were positive for CXCL9, whereas control tumor samples were negative for this chemokine." (PMID 21067607, 2010). "Indeed, a recent phase I clinical trial in six patients with multifocal recurrent GBM showed that the intrathecal injection of bivalent CAR-T cells targeting both IL-13Rα2 and EGFR led to tumor reduction in all patients, although none met the criteria for ORR." (PMID 39406966, 2024). "Moreover, intratumoral administration of GB-13 via CED decreased tumor burden and prolonged survival in both DMG and adult GBM intracranial murine xenografts with high, but not low levels of IL-13Rα2." (PMID 35631512, 2022).